RNU6-529P (RNA, U6 small nuclear 529, pseudogene)
Gene: Small nuclear RNA gene on chromosome 10 (87,041,238 to 87,041,341, reverse strand). Ensembl gene ENSG00000200253.
Homologues: Orthologues: chimpanzee U6 (99% identical). Paralogues in human: RNU6-29P (91% identical), RNU6-1124P (90% identical), RNU6-28P (90% identical), RNU6-1011P (89% identical), RNU6-1029P (89% identical), RNU6-1117P (89% identical), RNU6-12P (89% identical), RNU6-13P (89% identical), RNU6-230P (89% identical), RNU6-25P (89% identical), RNU6-32P (89% identical), RNU6-33P (89% identical), and 1289 more.